TTF1 (transcription termination factor 1)
Diseases named in the same sentence as TTF1 in open-access papers (continued):
Sharing a sentence is not in itself a finding about the gene and the disease.
lung adenocarcinoma (continued). "The IMIG guideline has suggested the use of Calretinin, D2–40, WT1, and CK5/6 as mesothelial markers, TTF-1, Napsin-A, Claudin 4, CEA as lung adenocarcinoma markers p40, p63, CK5/6, MOC-31 as squamous cell markers." (PMID 29317712, 2018). "For differential diagnosis between MM and lung adenocarcinoma, TTF-1, Napsin A, CEA, claudin 4 (CLDN4), Ber-EP4, and MOC31 are useful markers suggesting lung adenocarcinoma." (PMID 29538329, 2018). "The immunostains TTF-1, thyroglobulin, PAX8, and Napsin-A are markers that are used in the differential diagnosis of PTC from primary lung adenocarcinoma." (PMID 27774331, 2016). "For our patient, the lesion was immunoreactive for TTF-1, CK7, and cytokeratin AE1/AE3, favoring the diagnosis of adenocarcinoma of the lung." (PMID 26925278, 2016). "In Mirrielees report, TTF-1 was found to be expressed in 58 % of all NSCLC breast metastases and 83 % of those lung adenocarcinomas." (PMID 27488410, 2016). "The 6 papillary CNS metastases had a complete prior workup with IHCs confirming their origin, such as TTF1 and thyroglobulin for papillary thyroid carcinoma, TTF1, CK7, CK20 for lung adenocarcinoma, and Pax8, WT1, CK7, CK20 for serous carcinoma of the ovary." (PMID 27229317, 2016). "Currently, approximately 60% of lung adenocarcinomas have now been shown to have mutations (KIF5B-Ret, ROS1, NTRK1, HER2-Neu, to name a few) that may induce and drive these malignancies and the association of TTF-1 status and presence of these driver mutations remains to be elucidated." (PMID 25594059, 2014). "This study aims to detect the expressions of Napsin A, TTF-1, ERCC1, RRM1, EGFR, HER2, ERα, ERβ, PR, and Bcl-2 in lung adenocarcinoma and to explore their correlations with clinicopathological characteristics and prognosis." (PMID 24667263, 2014). "In the reported case, we elected to use to the TTF-1, CK7, CK20 immunohistochemical panel, which has recently been described as an effective means of differentiating lung adenocarcinoma from its metastases." (PMID 24716732, 2014). "A 48-year-old Caucasian male presented with a Stage IV, TTF1 positive, EGFR wild-type adenocarcinoma of the lung." (PMID 23617826, 2013). "The expression of EMT-related proteins including cytokeratin, E-cadherin, TTF-1, β-catenin, vimentin, Snail, Twist, CD44 was evaluated by immunohistochemistry using a tissue array method in the lung adenocarcinoma tissues of 95 patients." (PMID 23706092, 2013). "In this study, using a tissue array method, we investigated the expression of known EMT-related proteins including cytokeratin, E-cadherin, TTF-1, β-catenin, vimentin, Snail, Twist, CD44 in lung adenocarcinoma patients’ samples." (PMID 23706092, 2013). "Immunostaining with TTF-1, CDX2, CK7 and CK20 has been found to be helpful in highlighting occurrences of primary lung adenocarcinoma." (PMID 21308162, 2010). "In this case, because immunohistochemical analysis for TTF-1 and CK7/CK20 suggested that primary focus can either be thyroid cancer or lung adenocarcinoma, we used surfactant protein as a selective marker for the lung cancer." (PMID 18801198, 2008). "A sputum cell block confirmed lung adenocarcinoma (CK7+, TTF-1+)." (PMID 42005588, 2026). "Case one and case two were diagnosed as occult primary non-mucinous lung adenocarcinomas, based on the integration of morphological features and immunohistochemical co-expression of TTF-1 and Napsin A, despite the absence of identifiable lung lesions." (PMID 42279486, 2026). "The three lesions were biopsied, which revealed lesions that were positive for CK7 and TTF-1 and negative for p40, suggestive of lung adenocarcinoma." (PMID 40709141, 2025). "The first CUP showed features consistent with a squamous cell carcinoma, including p40 positivity, alongside histological evidence of lymph node involvement, whereas the second exhibited markers (e.g., TTF-1, CAM 5.2) typical of lung adenocarcinoma, suggestive of N2 disease with an occult primary." (PMID 40698218, 2025).
lung adenocarcinoma (continued). "Immunoreactivity for the lung adenocarcinoma markers thyroid transcription factor-1 (TTF1) and Napsin A, together with negative staining for the squamous cell carcinoma marker p63 confirmed that these lesions are adenocarcinomas." (PMID 40436847, 2025). "Immunohistochemical markers such as thyroid transcription factor-1 (TTF-1) and napsin A are typically positive in lung adenocarcinomas but negative in pancreatic adenocarcinomas." (PMID 40656425, 2025). "The subsequent positive TTF-1 immunohistochemistry further supported lung origin, as TTF-1 is expressed in approximately 85% of lung adenocarcinomas but is typically negative in pancreatic adenocarcinomas." (PMID 40656425, 2025). "A total of 6 lung adenocarcinoma samples from the 3 patients with double primary lung adenocarcinomas were all positive for TTF-1 and negative for HNF4α." (PMID 38710944, 2025). "TTF-1 (thyroid transcription factor-1) and napsin A are highly specific for lung adenocarcinomas and are negative in SCC." (PMID 40427131, 2025). "In the literature, SRGN is an important poor prognostic marker in lung adenocarcinoma negative for TTF1 expression (thyroid transcription factor 1), while in nasopharyngeal carcinoma, it was reported to be highly expressed in metastatic cases." (PMID 39273632, 2024). "TTF-1 antibody combined with dual-mode imaging AuNCs to form nanoprobe Au-TTF-1 through coupling reaction, which specifically recognized the highly expressed TTF-1 antigen in lung adenocarcinoma and light up lung adenocarcinoma cells with bright red FL." (PMID 38184620, 2024). "In the context of lung cancer, specifically non-small cell lung carcinoma (NSCLC), TTF-1 is expressed in nearly 75% of lung adenocarcinoma, whereas lung squamous cell carcinoma does not express TTF-1." (PMID 37775725, 2024). "The immunostains show positivity to TTF1, napsin A, and CK7 and negativity to PAX8 and CD10 of the neoplastic cells, sustaining a pulmonary phenotype; therefore, we signed the report as primary lung adenocarcinoma with clear cell features." (PMID 38256374, 2024). "Given that our patient's LUL nodule was negative for thyroid transcription factor-1 (TTF-1)/Napsin, which are reasonably sensitive and specific markers for adenocarcinoma of the lung, we placed adenocarcinoma lower on our differential diagnosis." (PMID 39691141, 2024). "Specifically, our cells are TTF-1 and NapA positive and p40 negative, and when used to generate orthotopic tumors, exhibit histology typical of solid human lung adenocarcinoma." (PMID 38994972, 2024). "Although our data show a very high sensitivity (94.1%) of TTF-1 IHC for lung adenocarcinomas, it is conspicuous that its specificity (86%) is not optimal for a safe separation of pulmonary adenocarcinomas from morphologically similar metastatic cancers." (PMID 39377914, 2024). "TTF-1 is often positive, indicating hepatoid differentiation and lung adenocarcinoma characteristics, although it is not essential for diagnosis." (PMID 39421450, 2024). "In comparison, SATB2 and CK20 showed higher specificity, with expression in 5% and 10% of mucinous primary lung adenocarcinomas and both in 0% of TTF-1-negative non-mucinous primary lung adenocarcinomas (25–50% and 5–16%, respectively, for GPA33/CDX2/CDH17)." (PMID 37349623, 2024). "Napsin A, TTF-1, and CK7 are all markers for lung adenocarcinoma in clinical practice." (PMID 38608841, 2024). "This retrospective cross-sectional laboratory study aimed to investigate the role of thyroid transcription factor-1 (TTF-1) in distinguishing lung adenocarcinomas from non-pulmonary adenocarcinomas in effusions." (PMID 37675165, 2023). "Immunohistochemical staining yielded positive results for thyroid transcription factor-1 (TTF-1) and napsin A and negative results for thyroglobulin, leading to the diagnosis of metastasis from lung adenocarcinoma." (PMID 37719531, 2023).
lung adenocarcinoma (continued). "The related markers of lung adenocarcinoma, including TTF1 and Napsin A, were both negative in SRCC, indicating that these two indicators are of great significance in the differential diagnosis." (PMID 37337182, 2023). "Two markers, TTF-1 and Napsin A, are undoubtedly specific and sensitive indicators for lung adenocarcinoma, and they were negative in five cases of breast cancer with signet ring cell differentiation." (PMID 37337182, 2023). "Unlike SMARCA4‐dNSCLC, classical lung adenocarcinomas are mostly TTF‐1 positive expression and HepPar‐1 negative expression, SMARCA4‐UTs are usually positive for stem cell markers and negative for epithelial markers." (PMID 37184108, 2023). "Positive TTF-1 was found in pleural fluid in 61.1 % of lung adenocarcinomas, while negative TTF-1 was found in only 3.4%." (PMID 37675165, 2023). "There is a scarcity of studies demonstrating the utility of the TTF-1 marker in distinguishing lung adenocarcinoma from non-pulmonary adenocarcinoma on a cytology basis." (PMID 37675165, 2023). "A core-needle biopsy was performed on the lesion in the left breast, and the pathological examination reported metastasis of lung adenocarcinoma (TTF-1: positive; GATA-3: negative) (Figure A1C,D)." (PMID 40733862, 2023). "TTF-1 is expressed in 75-85% of lung adenocarcinoma, but not in squamous cell carcinoma, so it is mainly utilized to distinguish adenocarcinoma from squamous cell carcinoma." (PMID 37710181, 2023). "The use of a commercial TTF-1 antibody product demonstrated positive TTF-1 expression in 11 out of 12 lung adenocarcinoma cases, while one non-pulmonary adenocarcinoma case showed positive TTF-1 expression." (PMID 37675165, 2023). "Poorly differentiated lung adenocarcinomas have been frequently reported as TTF-1-negative and occasionally labeled for ER, while individual cases of breast carcinoma may show TTF-1 staining." (PMID 36284362, 2022). "The positive staining of CK7 and TTF-1 combined with negative CK20 in our patient was highly suggestive of primary adenocarcinoma of the lung." (PMID 36039229, 2022). "The immunohistochemistry (IHC) results of this study showed that the lung cancer tissues of the CON group were positively stained for TTF-1, CEA was positively stained, and P63 was negatively stained, which indicates that the lung cancer induced by urethane is lung adenocarcinoma." (PMID 35371324, 2022). "However, about 30% of lung adenocarcinomas are TTF-1−, and TTF-1 is also expressed in other cancer types." (PMID 36499466, 2022). "Patients with positive TTF‐1 expression showed longer OS than those with negative TTF‐1 expression in stage I lung adenocarcinoma." (PMID 35808895, 2022). "A study on stage-four lung adenocarcinoma from the United States reported that TTF-1 immunostaining was a prognostic factor rather than a predictor of the response to platinum-doublet chemotherapy including PEM." (PMID 36614938, 2022). "Compared with ALK, EGFR, and TTF1, UCHL1 has higher predictive accuracy for lung adenocarcinoma." (PMID 35546675, 2022). "For metastatic MLA to the lung, the positive TTF1 staining and negative hormone receptors staining can be confused with a primary lung adenocarcinoma." (PMID 35865471, 2022). "For example, pemetrexed‐based chemotherapy, a standard treatment for nonsquamous NSCLC,13, 14, 15 was inferior to pemetrexed‐free regimens in lung adenocarcinoma patients with negative TTF‐1 expression." (PMID 35808895, 2022). "Characteristics of staining with TTF-1, Napsin-A and IGFR-1 in lung adenocarcinomas." (PMID 32876329, 2021).
lung adenocarcinoma (continued). "SRGN expression is transcriptionally upregulated by NRF2 activation and epigenetically induced through nicotinamide N-methyltransferase-induced perturbation of methionine metabolism in TTF-1–negative lung adenocarcinoma." (PMID 35008669, 2021). "TTF-1 is expressed mainly in 68–80% of primary lung adenocarcinomas, but expressed in less than 1% of adenocarcinomas of non-pulmonary origin." (PMID 33975638, 2021). "In a metastatic setting, like in our case, with metastasis to the lungs, the positive TTF1 staining and negative hormone receptors can be confusing with primary lung adenocarcinoma." (PMID 33670088, 2021). "He underwent a CT-guided biopsy of the RUL which was consistent with moderate to poorly differentiated lung adenocarcinoma staining positive for TTF-1 and Napsin A and negative for p63." (PMID 32560187, 2020). "Moreover, bioinformatics analysis of datasets in lung adenocarcinoma identifies the correlation of SLFN12 with other known lung adenocarcinoma markers like KRT7, Napsin A, and TTF-1." (PMID 32987632, 2020). "In this study, we demonstrated that TTF-1 expression was a good prognostic indicator for OS and PFS in patients with stage IV lung adenocarcinoma regardless of the presence or absence of EGFR mutations." (PMID 31196060, 2019). "TTF-1 expression was a good prognostic indicator for OS and PFS in stage IV lung adenocarcinoma patients with and without EGFR-sensitizing mutations." (PMID 31196060, 2019). "TTF-1 and Napsin A were expressed in all 7 cases, and metastatic lung adenocarcinoma was further supported with the negative results for PAX8, HNF-1β, ER and PR, and history of lung adenocarcinoma." (PMID 31455365, 2019). "Ordóñez found that TTF1 was negative in all patients with mesothelioma, but positive in 74% of patients with lung adenocarcinoma." (PMID 31528168, 2019). "Our present study indicated that TTF-1 expression was a good prognostic indicator for OS and PFS in patients with stage IV lung adenocarcinoma regardless of the presence or absence of EGFR mutations." (PMID 31196060, 2019). "We observed high expression of TUFT1 in TTF-1-negative A549 lung adenocarcinoma cells compared to TTF-1-positive NCI-H441 cells; furthermore, TUFT1 expression was strongly induced by TGF-β and the protein was located mainly in the cytoplasm." (PMID 29423269, 2018). "TTF-1 and Napsin-A expression were not present in any of 65 (0%) cases of epithelioid mesothelioma and only 54 (90%) cases and 48 (80%) cases of lung adenocarcinoma." (PMID 29317712, 2018). "For example, lung adenocarcinomas are frequently positive for TTF-1 and napsin, but PMEC are negative." (PMID 28463970, 2017). "TTF-1 and/or Napsin A stain lung adenocarcinoma whereas squamous cell carcinoma are not stained these antibodies." (PMID 28671973, 2017). "A biopsy from the lesion revealed an adenocarcinoma of the lung (TTF1-positive, negative for markers of neuroendocrine differentiation such as chromogranin A and synaptophysin 38)." (PMID 27776522, 2016). "Besides the advantage in the diagnosis of lung adenocarcinoma, both TTF-1 and Napsin A have also been found in biopsies of lung squamous cell carcinoma at rates of 2% to 13% for TTF-1, and upwards of 26% for Napsin A." (PMID 25003505, 2014). "Evaluation of metastatic lesions in mouse models show that TTF-1 is consistently depressed in metastatic versus non-metastatic lung adenocarcinoma." (PMID 25594059, 2014). "Napsin A, TTF-1, and ERCC1 are the markers indicating good prognosis of lung adenocarcinoma." (PMID 24667263, 2014). "Napsin A is a sensitive marker for lung adenocarcinoma, and a combination of TTF-1 and Napsin A may possibly be better than TTF-1 alone in confirming or excluding lung metastases to the breast." (PMID 23675755, 2013). "In Japan, a case of adenocarcinoma of the lung with metastasis was made after the bladder biopsy specimen was positive for TTF-1, and CK7 and negative for CK20." (PMID 23533933, 2013).
lung adenocarcinoma (continued). "Patients with strong TTF-1 protein expression group tend to have a significantly better prognosis than patients with negative and weak TTF-1 protein expression group in Xuanwei lung adenocarcinoma." (PMID 23514941, 2013). "TTF-1 is highly expressed in certain types of lung adenocarcinoma cell lines, including H441 cells and LC-2/ad cells, but not in A549 cells." (PMID 22111550, 2012). "In contrast, TTF-1 staining was seen in both the cytoplasm and nucleus when A549 cells were transfected with TTF-1, consistent with that observed in tissue sections of primary lung adenocarcinoma." (PMID 22940844, 2012). "Regarding the reactivity with other and lung malignancies, TTF-1 is not sufficient as a stand-alone marker for diagnosis of primary lung adenocarcinomas." (PMID 21811254, 2011). "Nevertheless, TTF1 has been reported to be negative in some mucin-producing primary lung adenocarcinoma." (PMID 21970610, 2011). "In this case, since the tumor specimen removed from the lung was negative in CK20 and Tg but positive in CK7 and TTF-1, it can be diagnosed as primary adenocarcinoma of the lung rather than lung metastasis from thyroid cancer." (PMID 21974801, 2011). "The pleura-invading lung adenocarcinoma, which expressed TTF-1 (arrow), was not stained with both anti-calretinin (arrow) and anti-intelectin (arrow)." (PMID 20628387, 2010). "Radiological imaging revealed nodular pleural thickening with loculated pleural effusion, while histopathological and immunohistochemical analyses confirmed pseudomesotheliomatous lung adenocarcinoma, distinguished by positive epithelial markers (TTF-1, Napsin A) and negative mesothelial markers." (PMID 42110081, 2026). "Thyroid transcription factor 1 (TTF-1) positivity is typically associated with NSCLC, however, several studies have shown that TTF-1 staining in the metastatic setting does not confirm lung origin, and in fact, ~20–40% of poorly-differentiated lung adenocarcinomas are TTF-1 negative." (PMID 40615718, 2025). "However, it is noteworthy that 29.4% of the 17 lung adenocarcinomas in our study were negative for TTF1." (PMID 40751531, 2025). "In contrast, the metastatic lung adenocarcinoma showed neoplastic cells with marked nuclear pleomorphism, intracytoplasmic eosinophilic hyaline globules, and TTF‐1 immunoreactivity, findings typically seen in lung adenocarcinoma with MET exon 14 skipping in an elderly female nonsmoker." (PMID 40028792, 2025). "Our previous report revealed that the main group of non-TRU-type lung adenocarcinomas were hepatocyte nuclear factor 4α (HNF4α)-positive adenocarcinomas with gastrointestinal features that frequently harbored KRAS mutations and TTF-1 inactivating mutations/hypermethylation." (PMID 38710944, 2025). "Thyroid transcription factor-1 (TTF-1) has long been recognized as a marker of lung adenocarcinoma, and retrospective studies have hinted that TTF-1-negative tumors might achieve inferior responses to chemotherapy and, possibly, immunotherapy." (PMID 40647486, 2025). "In addition, an excision biopsy was performed on the lesion of the right back, and the pathological examination showed metastasis of the lung adenocarcinoma (TTF-1: positive; ALK: negative; GATA-3: negative; CDX-2: negative) (Figure A1E,F)." (PMID 40733862, 2023). "In addition, compared with most lung adenocarcinomas, immunohistochemical features are the main distinguishing point for HCCC, which is negative for TTF-1 and napsin A, in contrast to lung adenocarcinomas." (PMID 37352028, 2023). "Among these, TTF-1 is a pneumocyte marker with high sensitivity and specificity for primary lung adenocarcinomas; TTF-1 is not expressed in every type of lung adenocarcinoma (Yoshimura) and, moreover, can also be positive in carcinomas from other sites, particularly depending on the antibody clone." (PMID 36835963, 2023).